ING2 (inhibitor of growth family member 2)
Description:
Component of a mSin3A-like corepressor complex, which is probably involved in deacetylation of nucleosomal histones. ING2 activity seems to be modulated by binding to phosphoinositides (PtdInsPs).
Synonyms: ING1Lp; ING1L; p33ING2
Tractability: Small molecule: a high-quality ligand is known. Antibody: its Gene Ontology location is reachable by antibodies, with high confidence. PROTAC: UniProt records ubiquitination sites on it; ubiquitination databases record sites on it; its protein half-life has been measured; a small molecule that binds it is known.
Target class: Plant homeodomain; Epigenetic regulator; Reader
Gene: Protein-coding gene on chromosome 4 (183,505,058 to 183,512,429, forward strand). Ensembl gene ENSG00000168556.
Subcellular location: Nucleus
Subcellular location (Human Protein Atlas): Nucleoplasm
Pathways (Reactome):
Metabolism of proteins: SUMOylation of transcription cofactors
Gene Ontology:
Molecular function: DNA binding; histone H3K4me3 reader activity; phosphatidylinositol binding; protein binding; protein-containing complex binding; chromatin binding; histone deacetylase regulator activity; histone reader activity
Biological process: positive regulation of DNA-templated transcription; positive regulation of transforming growth factor beta receptor signaling pathway; regulation of DNA-templated transcription; DNA damage response; flagellated sperm motility; male germ-line stem cell asymmetric division; male meiosis I; negative regulation of cell migration; negative regulation of gene expression, epigenetic; negative regulation of stem cell population maintenance; negative regulation of transcription by RNA polymerase II; negative regulation of transforming growth factor beta receptor signaling pathway; positive regulation of stem cell population maintenance; regulation of cellular senescence; seminiferous tubule development; signal transduction; spermatid development; spermatogenesis
Cellular component: CCAAT-binding factor complex; nucleoplasm; nucleus; plasma membrane; Sin3-type complex
Genetic constraint (gnomAD): Loss-of-function variants: 5 observed, 24.11 expected, observed/expected ratio (o/e) 0.21, 90% interval 0.11 to 0.44. The upper end of that interval is the gene's LOEUF score, 0.44, which puts it in group 1 of 6, group 1 being the genes least tolerant of losing a copy. Missense variants: 220 observed, 321.18 expected, observed/expected ratio (o/e) 0.68, 90% interval 0.61 to 0.77. Synonymous variants: 126 observed, 113.82 expected, observed/expected ratio (o/e) 1.11, 90% interval 0.96 to 1.28.
Homologues: Orthologues: chimpanzee ING2 (100% identical), macaque ING2 (100% identical), pig ING2 (99% identical), rabbit ING2 (99% identical), dog ING2 (98% identical), mouse Ing2 (97% identical), rat Ing2 (96% identical), guinea pig ING2 (96% identical), zebrafish ing2 (72% identical), tropical clawed frog ing2 (70% identical), Drosophila melanogaster CG7379 (38% identical), Caenorhabditis elegans lsy-13 (22% identical). Paralogues in human: ING1 (52% identical), ING3 (34% identical), ING5 (34% identical), ING4 (32% identical).
Diseases named in the same sentence as ING2 in open-access papers:
ING2 is named in the same sentence as 46 diseases in open-access papers, as found by Europe PMC text mining. Sharing a sentence is not in itself a finding about the gene and the disease. The quoted sentences say what the papers report.
lung carcinoma (6 papers, 2006 to 2019). "T to C substitution at codon 13 was detected in mutated bands in exon 1 of ING2, which occurred in 6 out of 31 lung cancer tissues." (PMID 31390718, 2019). "Summing up these findings, ING1 and ING2 are evidently expressed differentially in human lung cancer, as compared to healthy lung tissue." (PMID 31390718, 2019). "Consistently, studies also reported that ING2 was downregulated at the mRNA level in lung cancer cell lines." (PMID 31640185, 2019). "In the cell lines, mRNA of ING1b and/or ING2 was up-regulated in seven out of eight lung cancer cell lines, as compared to the normal bronchial epithelium cell line BETA2A." (PMID 31390718, 2019). "The results of this analysis revealed aberrant expression patterns of ING1b and ING2 in six out of 31 lung cancer tissue samples, and in only one out of 30 lung cancer cell lines, i.e., in the NSCLC cell line NCI-H23." (PMID 31390718, 2019). "It is worth noticing that ING2 degradation has been shown to be mediated by Smad 1 ubiquitination regulatory factor 1 (Smurf 1), a protein highly expressed in lung cancer." (PMID 31640185, 2019). "Concerning ING2, mRNA levels were found to be downregulated in breast ovarian, lung cancer and hepatocellular carcinoma, whereas ING2 protein was described to be downregulated in melanoma." (PMID 31878273, 2019). "According to this study, ING2 expression in lung cancer occurred infrequently, as compared to breast, ovarian, and endometrial cancer where the majority of cases expressed ING2." (PMID 31390718, 2019). "Expression of ING2 is decreased in several kinds of cancer including lung cancer, hepatocellular carcinoma and breast cancer." (PMID 29471858, 2018). "In the lung cancer samples, there was a shift of ING2 expression from the nucleus to the cytoplasm." (PMID 31390718, 2019). "However, these authors did not detect any ING2 mutation in 31 human lung cancer cell lines and 30 lung cancer biopsies." (PMID 16755297, 2006). "Similar to ING2, also ING3 was expressed in some lung cancer samples but occurred most abundantly in gynecological cancer entities." (PMID 31390718, 2019). "Notably, there is very limited data available on the effect of ING3 in lung cancer, whereas the function of ING1, ING2, ING4, and ING5 has been investigated in lung cancer in more detail." (PMID 31390718, 2019).
hepatocellular carcinoma (5 papers, 2018 to 2022). A malignant tumor that arises from hepatocytes. "Conversely, overexpression of the ING2 protein was found in patients with endometrial carcinoma and hepatocellular carcinoma (40/84)." (PMID 31640185, 2019). "At the transcriptomic level, studies found that ING2 mRNA was downregulated in several tumor types including basal cell carcinoma (75/75), hepatocellular carcinoma and osteosarcoma." (PMID 31640185, 2019). "Finally, at the genomic level, loss of heterozygosity (LOH) of the ING2 chromosomal region has been reported in ameloblastoma (14/28), head and neck squamous cell carcinoma (HNSCC) (30/55) (4q35.1), hepatocellular carcinoma (41.2%) (4q34–35.2), and basal cell carcinoma (3/11) (4q32-35)." (PMID 31640185, 2019). "Current notion suggested that ING2 might act as one crucial player in the pathogenesis of several tumors, such as non-small cell lung carcinoma, head and neck squamous cell carcinoma, and hepatocellular carcinoma, and serve as a potential pharmacologic target for these cancers as well." (PMID 34434929, 2021). "ING2, a member of inhibitor of growth (ING) family, is best known as a tumor suppressor for its expression is often lost or reduced in several tumors, such as non-small cell lung carcinoma, head and neck squamous cell carcinoma, and hepatocellular carcinoma." (PMID 34434929, 2021).
breast carcinoma (4 papers, 2012 to 2019). "Here, our results reveal that miR-8084 could promote EMT-associated migration in breast cancer; and ING2 may be a key mediator of this process." (PMID 29471858, 2018). "In this study we have found that ING1b and ING2 proteins differentially induce cell death and apoptosis in breast cancer cell lines compared to normal breast epithelial cells." (PMID 22916295, 2012). "As a potential regulator of ING2, it is reasoned that ectopic expression of miR-8084 could induce changes of biological phenotypes by reducing ING2 expression in breast cancer." (PMID 29471858, 2018). "Our results indicate miR-8084 functions as an oncomiR which is able to suppress apoptosis and promote cell growth, cell migration and invasion in breast cancer; and the target gene for miR-8084 to carry out its pro-tumor function is ING2, which is the first reported potential target of miR-8084." (PMID 29471858, 2018). "Furthermore, ING2 is also a favorable prognostic factor for survival in different subtype of breast cancer (including Basal, luminal A, luminal B and HER2-positive)." (PMID 29471858, 2018). "On the other hand, one publication suggested that the ING2 gene could be targeted on its 3′-UTR site by miR-8084, which showed tumor-promoting properties in breast cancer." (PMID 31640185, 2019).
soft tissue sarcoma (4 papers, 2010 to 2021). A malignant neoplasm arising from muscle tissue, adipose tissue, blood vessels, fibrous tissue, or other supportive tissues excluding the bones. "Importantly, Ing2−/− mice were afflicted by increased soft-tissue sarcoma, demonstrating that loss of Ing2 is sufficient to increase tumorigenicity and that Ing2 is likely a bona fide tumour suppressor." (PMID 33925563, 2021). "In addition, loss of Ing2 resulted in high incidence of soft-tissue sarcomas, particularly histiocytic sarcomas, demonstrating, for the first time, a tumor suppressor role for Ing2." (PMID 21124965, 2010). "Investigations in transgenic mouse models have so far seemed to confirm that Ing1 and Ing2 are tumour suppressor genes, respectively preventing lymphomas and soft-tissue sarcomas." (PMID 33925563, 2021). "In recent years, ING1 and ING2 have been described as tumor suppressor genes in various human cancer types, and both ING1 and ING2 knockout mice were found to spontaneously develop malignant diseases such as B cell lymphomas and soft tissue sarcomas." (PMID 31390718, 2019). "Similarly, the Ing2−/− animals have a threefold higher incidence of soft-tissue sarcomas, providing concrete evidence that at least Ing1 and Ing2 are bona fide tumour suppressors." (PMID 29381681, 2018). "In addition, a bona fide tumor suppressive role of Ing2 is demonstrated by increased incidence of soft-tissue sarcomas in Ing2−/− mice." (PMID 21124965, 2010). "Thus, we currently conclude that Ing2 deficiency by itself does not affect aging phenotypes but enhances spontaneous formation of soft-tissue sarcomas." (PMID 21124965, 2010).
colon cancer (3 papers, 2019 to 2023). "On one hand, ING2 upregulation at the mRNA level was reported in patients with colon cancer (18/34), even if the underlying mechanism was not investigated in this study." (PMID 31640185, 2019). "Additionally, NF-kB can bind to the ING2 promoter region and activate ING2 transcription in colon cancer." (PMID 31640185, 2019). "Moreover, studies on tumor cell lines also found that ING2 was overexpressed in cervical carcinoma, colon cancer, and acute lymphoblastic leukemia (ALL) cell lines." (PMID 31640185, 2019). "The upregulation of ERK/NF-κB signalling enhanced the binding of NF-κB to Inhibitor of growth 2 (ING2) promoter, leading to the activation of ING2, which subsequently increased MMP-13 expression in colon cancer." (PMID 35805035, 2022).
esophageal cancer (3 papers, 2018 to 2021). A primary or metastatic malignant neoplasm involving the esophagus. "Hypermethylation of CASZ1, CDH13 and ING2 detected in plasma cell-free DNA can be applied as a potential noninvasive biomarker for diagnosis of esophageal cancer." (PMID 30355852, 2018). "Hypermethylation of CASZ1, CDH13 and ING2 genes detected using cell-free DNA in blood samples can be applied as a potential biomarker for the diagnosis of esophageal cancer." (PMID 30355852, 2018).
Infertility (3 papers, 2010 to 2025). "Genetic and epigenetic changes, as well as functional variants, of the ING2 gene itself also deserve investigation in infertile men." (PMID 21124965, 2010). "Consistent with its abundant expression in mouse and human testes, male mice deficient for Ing2 showed abnormal spermatogenesis and were infertile." (PMID 21124965, 2010). "It is unknown whether an altered expression of one or a few specific genes or a genome-wide change in chromatin status mediates the defects in Ing2-deficient mice, as well as in other infertile mice deficient for chromatin modifying factors." (PMID 21124965, 2010). "We compared nine types of infertility in male humans and mice, including MArrest, oligospermia and teratospermia in humans and Ing2 Knockout (KO), Bcl6 KD, Etv5 KD, Pou3f1 KD, Ikbkap KO and Dazap1 mutant in mice." (PMID 29150651, 2017). "The relevance in humans is underscored by bioinformatics analysis revealing low ING2 expression in men with infertility and defective spermatogenesis." (PMID 21124965, 2010). "Two datasets (GSE6967 and GSE6872) comparing spermatozoa purified from semen samples of infertile teratozoospermic men versus normal fertile men showed significantly lower levels of ING2 expression in the former cases." (PMID 21124965, 2010). "Additionally, the Arpc1b gene was up-regulated in Bcl6b, Etv5, Pouf31 and Dazap1 KD, and Alcam was up-regulated in Bcl6b, Etv5, Pouf31 and Ing2 KD infertile mice." (PMID 29150651, 2017).
male infertility (3 papers, 2010 to 2021). The inability of the male to effect fertilization of an ovum after a specified period of unprotected intercourse. "Furthermore, a decreased ING2 expression level is also associated with defective spermatogenesis and male infertility in humans." (PMID 33407810, 2021). "Consequently, this defect in spermatogenesis of ING2-deficient mice led to male infertility indicating an essential role for ING2 in meiosis." (PMID 21767350, 2011). "This association does not per se indicate a causative role for ING2 deficiency in human male infertility." (PMID 21124965, 2010).
melanoma (3 papers, 2006 to 2020). A malignant, usually aggressive tumor composed of atypical, neoplastic melanocytes. "Using the tissue microarray technology and immunohistochemistry, we for the first time demonstrated that ING2 nuclear expression is reduced in human melanomas compared to dysplastic nevi." (PMID 16755297, 2006). "In primary melanomas, 79 cases (50 male subjects and 29 female subjects) were available for the evaluation of ING2 staining." (PMID 16755297, 2006). "We examined ING2 nuclear expression in normal nevi, dysplastic nevi, primary melanomas and metastatic melanomas by immunohistochemistry." (PMID 16755297, 2006). "As UV radiation is the main environment factor for melanoma formation, reduced ING2 expression would impair the removal of UV-damaged DNA, leading to gene mutation and malignant cell transformation." (PMID 16755297, 2006). "We also used AJCC criteria to evaluate ING2 expression among 122 melanomas (79 primary melanomas and 43 metastatic melanomas), 41 tumours were at stage I, 34 at stage II, 24 at stage III and 23 at stage IV." (PMID 16755297, 2006). "Our results for the first time showed that nuclear ING2 expression was reduced in melanoma biopsies compared to dysplastic nevi." (PMID 16755297, 2006). "Here, we used tissue microarray technology and immunohistochemistry to examine ING2 expression in human nevi and melanoma biopsies." (PMID 16755297, 2006). "On the other hand, although it is not statistically significant, we observed that patients with weaker ING2 expression have a trend towards better prognosis for both overall and disease-specific 5-year patient survival in primary melanomas." (PMID 16755297, 2006). "ING3 protein, as well as its homolog ING2, has been shown to be downregulated in melanoma." (PMID 31878273, 2019). "We have recently demonstrated that ING2 plays an essential role in cellular stress response to UV irradiation either by enhancing nucleotide excision repair or promote UV-induced apoptosis in melanoma cell lines." (PMID 16755297, 2006). "Taken together, our results suggest that nuclear ING2 expression is significantly reduced in human melanomas and that reduced ING2 may be an important molecular event in the initiation of melanoma development." (PMID 16755297, 2006). "Although the reason for reduced ING2 expression in human melanomas is unclear, we cannot rule out mutation of the ING2 gene in melanoma because different tumour type may have different mechanisms for gene inactivation." (PMID 16755297, 2006). "Reduced ING2 expression was observed in RGP and VGP primary melanomas as well as metastatic melanomas compared with dysplastic nevi (P=0.029, 0.0001 and 0.0286, respectively, Mann–Whitney test)." (PMID 16755297, 2006). "Future studies on the correlation between ING2 expression and patient survival in a large set of melanoma biopsies from patients with and without chemotherapy will provide a clearer answer." (PMID 16755297, 2006). "Similar levels of ING2 nuclear expression in melanomas regardless of the growth phases (RGP vs VGP), tumor thickness, ulceration or AJCC staging suggest that reduced ING2 expression may be involved in the initiation, rather than progression of melanoma." (PMID 16755297, 2006).
osteosarcoma (3 papers, 2019 to 2021). A usually aggressive malignant bone-forming mesenchymal neoplasm, predominantly affecting adolescents and young adults. "Thus, the difference between HK2 cells and osteosarcoma cells in metabolic profiles might contribute to the different effects of ING2 on mtDNA transcription." (PMID 34434929, 2021). "Hence, I have compared the prognostic gene set for osteosarcoma, Cox univariate and multivariate analysis showed that BACE2, ING2 ALOX5AP, HLA-DMB, HLA-DRA, and SPINT2 were not the independent prognostic factors for osteosarcoma." (PMID 33520450, 2021).
B cell lymphomas (2 papers, 2010 to 2019). "Furthermore, while Ing1−/− mice had elevated incidence of B-cell lymphomas, Ing2−/− mice had elevated incidence of histiocytic sarcoma." (PMID 21124965, 2010).
basal cell carcinoma (2 papers, 2006 to 2019). A carcinoma involving the basal cells. "In addition, loss of heterozygosity of the region 4q32 in the long arm of chromosome 4, which includes ING2 and SAP30, was found in 20% of basal cell carcinomas, suggesting that genetic alteration of the ING2 gene does occur in human tumours." (PMID 16755297, 2006).
prostate carcinoma (2 papers, 2021 to 2024). A carcinoma that arises from epithelial cells of the prostate gland. "Additionally, ING1 and ING2, through their recruitment by the AR, have been shown to orchestrate the downregulation of the human telomerase reverse transcriptase subunit (hTERT) in prostate cancer cells." (PMID 38813086, 2024).